Y_RNA (Y RNA )
Gene: Miscellaneous RNA gene on chromosome 5 (96,962,656 to 96,962,757, reverse strand). Ensembl gene ENSG00000200884.
Homologues: Orthologues: macaque Y_RNA (96% identical), chimpanzee Y_RNA (83% identical). Paralogues in human: Y_RNA (87% identical), RNY3 (86% identical), Y_RNA (86% identical), RNY3P1 (85% identical), Y_RNA (85% identical), RNY3P14 (84% identical), Y_RNA (84% identical), Y_RNA (83% identical), Y_RNA (82% identical), RNY3P11 (81% identical), Y_RNA (81% identical), RNY3P16 (80% identical), and 94 more.